NLRP3 (NLR family pyrin domain containing 3)
Diseases named in the same sentence as NLRP3 in open-access papers (continued):
Sharing a sentence is not in itself a finding about the gene and the disease.
fibrosarcoma (6 papers, 2013 to 2022). A malignant mesenchymal fibroblastic neoplasm affecting the soft tissue and bone. "For instance, in mouse models of methylcholanthrene (MCA, a highly potent carcinogen) induced fibrosarcoma, NLRP3 was demonstrated to promote cancer progression." (PMID 25071785, 2014). "In contrast to the protective role of NLRP3 in CAC, NLRP3 was shown to promote tumor formation in a chemical-induced fibrosarcoma model." (PMID 24273542, 2013). "Similarly, the lack of IL-1R helped to protect mice from MAC-induced fibrosarcoma, and the same result could be observed in Nlrp3−/− or Caspl−/− mice; this may be related to NLRP3 inhibiting the function of NK cells." (PMID 35733919, 2022).
invasive breast carcinoma (6 papers, 2016 to 2025). A carcinoma that infiltrates the breast parenchyma. "Another study indicated that the inhibition of the NLRP3 inflammasome stimulated the recruitment and activation of Natural Killer cells in invasive breast cancer model, independently of IL-1β and IL-18 signaling." (PMID 39433537, 2024). "The expression levels of the NLRP3, PYCARD and TLR4 were determined by immunohistochemistry in a cohort of primary invasive breast carcinomas (BCs)." (PMID 34540671, 2021).
laryngeal squamous cell carcinoma (6 papers, 2019 to 2023). A squamous cell carcinoma that arises from the larynx. "For example, increased NFE2L2 and TMB pathway changes were linked to radiation resistance in laryngeal squamous cell carcinoma (LSCC), and NLRP3 activation could promote carcinogenesis and chemoresistance in HNSCC, and ATP7B upregulation promoted chemoresistance of HNSCC." (PMID 36620545, 2022). "However, the role of NLRP3 inflammasome in laryngeal squamous cell carcinoma (LSCC) remains unclear." (PMID 31312615, 2019).
liver cirrhosis (6 papers, 2019 to 2025). "Here we showed that hepatocyte undergoing pyroptosis was mediated by NLRP3 in liver cirrhosis." (PMID 35634294, 2022). "Immunohistochemical assays showed that NLRP3, GSDMD, caspase-1 and CK19 were more highly expressed in the liver cirrhosis group than in the other groups, and the levels in the medium and high dose Exo-rBMMSC groups were dramatically decreased." (PMID 36552767, 2022). "Mechanistically, NLRP3 inflammasome-activated GSDMD and its pyroptosis were upregulated in liver cirrhosis, while SHED infusion could suppress the expression of GSDMD and Caspase-1, resulting in reduced hepatocyte pyroptosis and inflammatory cytokine IL-1β release." (PMID 35634294, 2022). "Quantitative analysis showed that NLRP3-positive cells in the high dose Exo-rBMMSC group were significantly reduced compared to those in the liver cirrhosis group (*** p < 0.001), but were not significantly different compared to those in the low and medium dose Exo-rBMMSC groups (p > 0.05)." (PMID 36552767, 2022).
lymph node metastasis (6 papers, 2018 to 2024). "It has been shown that amplification of the NLRP3 inflammasome components was reduced in S1PR1-deficient TAMs suggesting that NLRP3 regulation in TAMs was associated with lymph node metastasis and prognosis." (PMID 30447690, 2018). "The risk of BLCA, tumor size, and lymph node metastasis are all related to the NLRP3 polymorphism." (PMID 37424068, 2023). "Furthermore, correlation analysis of NLRP1/NLRP3 with clinical features showed that high expression of NLRP1/NLRP3 correlated significantly with worse prognosis in GC patients with lymph node metastasis." (PMID 36541912, 2022). "Meanwhile, in the positive group of ESCC patients, lymph node metastasis occurred early, infiltration was deep, and the clinical stage occurred late, suggesting that Fn infection, high NLRP3 expression, and MDSCs enrichment may promote the malignant progression of ESCC." (PMID 35435776, 2022). "The chi-square test showed that Fn infection, high NLRP3 expression and MDSCs enrichment were related to sex, smoking status, drinking consumption, differentiation degree, invasion depth, lymph node metastasis and clinical stage but not to age." (PMID 35435776, 2022).
macrophage activation syndrome (6 papers, 2015 to 2026). A complication of rheumatic disease that is caused by excessive activation and uncontrolled proliferation of T lymphocytes and well-differentiated macrophages. "The disease was termed Nlrc4-macrophage activation syndrome (Nlrc4-MAS) and shares similarity to mutations in the NLRP3 gene that result in the autoinflammatory disease, neonatal onset multisystem inflammatory disease (NOMID)." (PMID 26635450, 2015). "For example, pyrin and NLRP3 are widely expressed in innate immune cells and activate pro-IL-1β, while NLRC4 is expressed in the gut and has pro-IL-18 as substrate, contributing to the development of severe enterocolitis and macrophage activation syndrome (MAS)." (PMID 34198614, 2021).
myeloproliferative neoplasm (6 papers, 2020 to 2025). A clonal hematopoietic stem cell disorder, characterized by proliferation in the bone marrow of one or more of the myeloid (i.e., granulocytic, erythroid, megakaryocytic, and mast cell) lineages. "NLRP3 has a crucial role in myeloproliferative neoplasms (MPNs), considered to be the diseases best studied in the inflammasome context." (PMID 36902299, 2023). "Overall, activation of the NLRP3 inflammasome by cellular labile iron might have broad implications for iron overload and chronic inflammation in myeloproliferative disorders." (PMID 33429941, 2021). "Furthermore, oncogenic KRAS mutations were shown to induce NLRP3 via upstream activation of RAC1 GTPase and subsequent generation of reactive oxygen species (ROS), implicating upregulation of the RAC1/ROS/NLRP3/IL-1β axis as a crucial event in myeloproliferative disorders." (PMID 39223663, 2024).
neuromyelitis optica spectrum disorder (6 papers, 2019 to 2024). "The utility of NLRP3 as a potential biomarker in MS is further supported by another study demonstrating elevated NLRP3 in neuromyelitis optica spectrum disorders." (PMID 32878648, 2020).
obstructive sleep apnea (6 papers, 2021 to 2024). "It has also been observed that galectin-3 levels increase significantly in patients with Obstructive Sleep Apnea (OSA), and this increase further promotes neuroinflammation and oxidative stress via regulating NLRP3." (PMID 38755574, 2024).
ovarian endometriosis (6 papers, 2022 to 2025). A non-neoplastic disorder characterized by the growth of endometrial tissue in the ovaries. "NLRP3 expression is significantly higher in ovarian endometriosis, and using an NLRP3 inhibitor has effectively reduced ovarian endometriosis lesions in animal models." (PMID 40508002, 2025). "Increased expression of NLRP3 inflammasome and activation of IL-1β has been associated with the progression of ovarian endometriosis, and inhibitor NLRP3 using MCC950 prevents ovarian endometriosis." (PMID 39769450, 2024). "Similarly, MCC950 (an NLRP3 inhibitor) prevents ovarian endometriosis and the expression of NLRP3 and IL-1β in the endometrial stromal cells and cyst-derived stromal cells." (PMID 39769450, 2024). "administered the NLRP3 inhibitor MCC950 to ovarian endometriosis (OE) mice and showed that inhibition of NLRP3 inflammasome activity reduced the expression of IL-1β and Ki67 in cyst-derived stromal cells (CSCs), leading to a significant inhibition of OE lesion size." (PMID 37965452, 2023).
overnutrition (6 papers, 2017 to 2023). An imbalanced nutritional status resulting from excessive intake of nutrients. "Here, we address the role of maternal overnutrition as a trigger for central and peripheral immune training and its contribution to neurodegeneration and the molecular nodes implicated in the Nod-like receptor protein 3 (NLRP3) inflammasome pathway leading to immune training." (PMID 32116490, 2020). "Overnutrition induces β-cell dysfunction affecting insulin secretion through mitochondrial ROS generation and NLRP3 activation." (PMID 37599368, 2023). "ApoE deficiency improved hyperinsulinemia and glucose tolerance in HFD feeding couples, which promoted overnutrition-induced metabolic inflammation in adipose tissue through NLRP3 inflammasome." (PMID 38062308, 2023). "NLRP3 is an innate immune sensor capable of instigating an inflammatory cascade in response to multiple stressors, such as overnutrition." (PMID 38062308, 2023). "More recently, an NLRP3 selective inhibitor improved NAFLD pathology either in the appetite-defective foz/foz mice overnutrition model fed an atherogenic diet or in the MCD model." (PMID 28939830, 2017). "Consequently, the presence of NLRP3 exacerbated tubular oxidative stress, mitochondrial damage and malabsorption during overnutrition." (PMID 28588189, 2017).
pneumococcal pneumonia (6 papers, 2015 to 2023). A febrile disease caused by STREPTOCOCCUS PNEUMONIAE. "In lung tissues during early pneumococcal pneumonia, NLRP3 appears to play an increasingly important role in protective immunity as infection duration and bacterial burden increase." (PMID 35111047, 2021). "The NLRP3 inflammasome is an important mediator of innate immunity during pneumococcal pneumonia." (PMID 26317436, 2015). "Finally, a more recent study showed that transgenic overexpression of Mincle in mice led to activation of the NLRP3 inflammasome, leading to increased lung injury and fatality in response to pneumococcal pneumonia, which could be abrogated through NLRP3 inflammasome inhibition." (PMID 36829255, 2023). "The amelioration of inflammatory responses in the lung during pneumococcal pneumonia by ibrutinib may also result from inhibition of other Btk-dependent receptors that regulated S. pneumoniae-induced lung inflammation, including TLR4, TLR9, TREM-1 and NLRP3." (PMID 30646846, 2019).
post-traumatic stress disorder (6 papers, 2020 to 2025). An anxiety disorder precipitated by an experience of intense fear or horror while exposed to a traumatic (especially life-threatening) event. "Moreover, NLRP3 inflammasome activation was also associated with the development of posttraumatic stress disorder (PTSD)." (PMID 37637999, 2023). "Animal models of post-traumatic stress disorders present activation of NLRP3 inflammasome in astrocytes sorted from glial fibrillary acidic protein (GFAP) transgenic mice, while administration of leptin markedly suppressed the activation of astrocytic NLRP3 inflammasome." (PMID 36674935, 2023).
retinal disease (6 papers, 2020 to 2025). "Lipofuscin accumulation can trigger RPE cell apoptosis via NLRP3 inflammasome activation, lysosomal proton pump inhibition and lysosome alkalization, and is linked to retinal diseases such as Stargardt disease and AMD." (PMID 38765984, 2024). "Though several methods have been developed to detect inflammasome activation by imaging caspase-1 and other mediators activity in vitro and in vivo, applications to detect NLRP3 inflammasomes in retinal diseases have been limited." (PMID 36703888, 2022). "In sharp contrast, both RIPK1 and RIPK3 proteins were detected within MCMV-infected of wildtype MAIDS-10 mice, as well as MCMV-infected eyes of MAIDS-10 mice deficient in either NLRP3, NLRP1b, or AIM2, all of which exhibited an atypical pattern of retinal disease." (PMID 41011779, 2025). "NLRP3 inflammasome plays a crucial role in triggering the inflammatory response in retinal disease." (PMID 40469974, 2025). "In comparison, histopathologic analysis of MCMV-infected eyes of groups of NLRP3−/− MAIDS-10 mice, NLRP1b−/− MAIDS-10, and AIM2−/− MAIDS-10 mice all consistently showed a consistent and similar pattern of atypical retinal disease." (PMID 41011779, 2025). "Whilst the present study suggests that NLRP3 is instrumental in DR-mediated RPE damage, more studies are required to fully elucidate NLRP1 inflammasome involvement in retinal diseases." (PMID 33396676, 2020). "Importantly, MCMV-infected eyes of MAIDS-10 mice deficient in either caspase-1, GSDMD, or IL-18 all consistently showed a pattern of retinal disease similar, if not identical, to that observed in the present study for MAIDS-10 mice deficient in the NLRP3, NLRP1b, or AIM2 inflammasomes." (PMID 41011779, 2025).
schistosomiasis (6 papers, 2016 to 2025). An infectious disease caused by parasitic trematodes of the genus Schistosoma that colonize human blood vessels and release eggs that can cause granulomatous reactions leading to acute (swimmer's itch or acute schistosomiasis syndrome) or chronic disease. "A pathogenic role for NLRP3 in inducing inflammation in schistosomiasis has been reported by various groups." (PMID 38559160, 2024). "Our findings establish NLRP3/AIM2-Gsdmd axis as a central inducer of pathogenic Th17 responses which is counteracted by IFN-I pathway in schistosomiasis." (PMID 38559160, 2024). "The main purpose of this study was to use NLRP3 inflammasome inhibitor, MCC950, to block liver granuloma and fibrosis that resulted from S. japonicum in order to uncover the underlying molecular mechanism and potential treatments for schistosomiasis." (PMID 30635040, 2019). "Pretreatment of NLRP3-/- and AIM2-/- BMDCs with IFN-I receptor blocking antibody led to a marked increase in IL-1β and IL-17 production, demonstrating a novel mechanism by which IFN-I signaling regulates inflammation in schistosomiasis." (PMID 40100932, 2025).
skin infection (6 papers, 2012 to 2025). An inflammatory process affecting the skin, caused by bacteria, viruses, parasites, or fungi. "Female mice have been shown to be protected from dermonecrosis in a model of invasive MRSA skin infection due to reduced expression of genes associated with the NLRP3 inflammasome (Nlrp3 and Il1β) compared to males." (PMID 40197396, 2025). "The NLRP3 inflammasome was found to promote IL-1β activation at the site of S. aureus skin infection in mice by mediating neutrophil recruitment to the site of skin infection." (PMID 35878202, 2022). "The reduced IL-10 levels could be allowing amplified NLRP3 activation and IL-1β production during S. aureus skin infection." (PMID 38973612, 2024). "Furthermore, PGN strongly induces NLRP3 inflammasome expression in macrophages in S. aureus skin infections." (PMID 35878202, 2022). "Further, patients with SNPs in CD207 of Langerhans cells or NLRP3 of phagocytes may be more prone to skin infections." (PMID 36636720, 2022).
squamous cell carcinoma (6 papers, 2017 to 2024). A carcinoma arising from squamous epithelial cells. "Some studies have shown that NLRP3 inflammasome activation promotes the progression of squamous cell carcinoma (SCC) by fostering a pro-inflammatory environment." (PMID 39839625, 2024). "On the other hand, silencing the NLRP1 and NLRP3 gene changed the expression of these squamous cell carcinoma proteins marker genes as well as basal cell carcinoma proteins such as Gli1, Gli2, FOXO3A." (PMID 39839625, 2024). "Dynamic single-cell profiling of human squamous cell carcinoma delineates specific efferocytosis gene set enriched tumor-infiltrating mononuclear phagocytes that transition to distinct myeloid cells with high upregulation of NLRP3." (PMID 36439171, 2022). "Tgfbr1 and Pten were able to inhibit the expression of NLRP3, ASC, caspase-1, IL-1β, and IL-18 in a mouse squamous cell carcinoma of the head and neck model." (PMID 32723297, 2020). "Moreover, a significant increase in squamous cell carcinoma proteins marker genes such as SerpinA1, SerpinA3 and EphB2 under the influence of UV radiation was observed in cells with efficiently functioning NLRP1 and NLRP3." (PMID 39839625, 2024).
urinary tract infection (6 papers, 2018 to 2025). "The inflammasome-associated proteins caspase-1, caspase-4 and NLRP3 have been emphasised to be essential in the host cell response during urinary tract infection (UTI) by regulating IL-1β release." (PMID 35132157, 2022). "The inflammasome-associated proteins caspase-1, caspase-4 and NLRP3 have been emphasised to be vital in the host response during urinary tract infection by regulating IL-1β release." (PMID 35132157, 2022). "The NLRP3 inflammasome and IL-1β have recently been linked to the severity of uropathogenic Escherichia coli (UPEC)-mediated urinary tract infection (UTI)." (PMID 33318544, 2020). "The NLRP3 inflammasome and IL-1β release have recently been suggested to be important for the progression of urinary tract infection (UTI)." (PMID 29662840, 2018). "However, research on the other components regarding the NLRP3 inflammasome and urinary tract infections is still lacking." (PMID 40004227, 2025).
Acute hepatitis (5 papers, 2017 to 2025). Acute hepatic injury resulting from inflammation typically accompanied by increased serum alanine transaminase activity. "Aspartate (Asp) can act on liver Kupffer cells, inhibit NOD-like receptor-P 3 (NLRP3) inflammatory bodies, and improve liver inflammation in acute hepatitis." (PMID 36983568, 2023). "Furthermore, miR-223-3p negatively regulates activation of the NLRP3 inflammasome by downregulating expression of NLRP3, IL-1β, and activation of caspase-1 in both endotoxin acute hepatitis and fibrotic NASH." (PMID 35371024, 2022). "CA nanoparticles have also demonstrated the ability to reduce inflammation and apoptosis in acute hepatitis models by decreasing levels of TNF-α, IL-1β, and IL-18, as well as inhibiting NF-κB, NLRP3, and caspase-1, while promoting Bcl-2 levels." (PMID 40869259, 2025).
adenovirus infection (5 papers, 2010 to 2024). "NLRP3 activation affects the immune response by regulating the release of inflammatory mediators and plays an antiviral role in adenovirus infection." (PMID 38399989, 2024). "In addition, adenovirus infection shows that the activation of NLRP3 is related to the regulation of an inflammatory response." (PMID 38399989, 2024). "In addition, the levels of the inflammasome NLRP3 and the inflammatory marker iNOS were measured to establish the effects of adenovirus infection." (PMID 34209378, 2021). "Expression of NLRP3 in THP-1 cells at the end-point of the experimental setup was relatively unaffected by inflammasome activation and adenovirus infection." (PMID 31849970, 2019).
anaphylaxis (5 papers, 2012 to 2024). An acute hypersensitivity reaction that occurs from exposure to an allergen. "IgE-Ag-triggered anaphylaxis was prevented by an NLRP3 inhibitor." (PMID 38486019, 2024).
anemia (5 papers, 2009 to 2025). A reduction in the number of red blood cells, the amount of hemoglobin, and/or the volume of packed red blood cells. "Degradation of GATA1 downstream of NLRP3 inflammasome activation has been proposed as a mechanism leading to anemia in MDS37." (PMID 41298546, 2025). "MK/platelet NLRP3 inflammasome promotes the acute inflammatory response and its hyperactivation in mice leads to mild anemia and increased extramedullary erythropoiesis." (PMID 37622117, 2023). "Whether DAMP-triggered NLRP3 inflammasome activation and subsequent pyroptosis represents an additional factor contributing to anemia and cytopenias in MF, as demonstrated for MDS, remains to be determined." (PMID 39391311, 2024). "In addition, G-CSF blocks erythropoiesis in the BM, which could potentially worsen anemia in the context of MK/platelet NLRP3 hyperactivation." (PMID 37622117, 2023). "In conclusion, we report that IL-1β over-secretion caused by activated NLRP3 inflammasome in myeloid cells, but not mesenchymal cells, drives anemia, and hypoxia in the bone environment, ultimately promoting chondrocyte death, and the development of abnormal growth plate and epiphysis." (PMID 28687790, 2017). "In unchallenged mice, hyperactivity of MK/platelet NLRP3 resulted in mild anemia, surprisingly, without affecting platelet numbers or function." (PMID 37622117, 2023).